FRK (fyn related Src family tyrosine kinase)
Description:
Non-receptor tyrosine-protein kinase that negatively regulates cell proliferation. Positively regulates PTEN protein stability through phosphorylation of PTEN on 'Tyr-336', which in turn prevents its ubiquitination and degradation, possibly by reducing its binding to NEDD4. May function as a tumor suppressor.
Synonyms: PTK5; RAK; GTK
Tractability: Small molecule: an approved drug acts on it; a high-quality ligand is known; it belongs to a druggable protein family. Antibody: its Gene Ontology location is reachable by antibodies, with high confidence. PROTAC: its protein half-life has been measured; a small molecule that binds it is known.
Target class: Kinase; TK protein kinase group; Enzyme; Protein Kinase; Tyrosine protein kinase Src family
Gene: Protein-coding gene on chromosome 6 (115,931,149 to 116,061,093, reverse strand). Ensembl gene ENSG00000111816.
Subcellular location: Cytoplasm; Nucleus
Subcellular location (Human Protein Atlas): Nucleoplasm; Cytosol
Pathways (Reactome):
Immune System: Neutrophil degranulation
Signal Transduction: Regulation of PTEN stability and activity
Gene Ontology:
Molecular function: protein binding; protein tyrosine kinase activity; non-membrane spanning protein tyrosine kinase activity; signaling receptor binding; ATP binding; protein kinase activity
Biological process: negative regulation of transcription by RNA polymerase II; cell differentiation; cell surface receptor protein tyrosine kinase signaling pathway
Cellular component: cytoplasm; extracellular exosome; nucleoplasm; azurophil granule lumen; cytosol; extracellular region; nucleus; plasma membrane; specific granule lumen
Genetic constraint (gnomAD): Loss-of-function variants: 48 observed, 60.07 expected, observed/expected ratio (o/e) 0.8, 90% interval 0.63 to 1.02. The upper end of that interval is the gene's LOEUF score, 1.02, which puts it in group 4 of 6, group 1 being the genes least tolerant of losing a copy. Missense variants: 519 observed, 589.23 expected, observed/expected ratio (o/e) 0.88, 90% interval 0.82 to 0.95. Synonymous variants: 229 observed, 217.06 expected, observed/expected ratio (o/e) 1.05, 90% interval 0.95 to 1.18.
Homologues: Orthologues: chimpanzee FRK (99% identical), mouse Frk (90% identical), rat Frk (88% identical), pig FRK (88% identical), macaque FRK (87% identical), dog FRK (80% identical), guinea pig FRK (74% identical), rabbit FRK (67% identical), tropical clawed frog frk (62% identical), zebrafish frk (60% identical). Paralogues in human: FYN (50% identical), FGR (50% identical), HCK (48% identical), YES1 (48% identical), LYN (48% identical), SRC (48% identical), LCK (46% identical), BLK (45% identical), ABL2 (40% identical), PTK6 (40% identical), ABL1 (39% identical), SRMS (39% identical), and 20 more.
Diseases named in the same sentence as FRK in open-access papers:
FRK is named in the same sentence as 31 diseases in open-access papers, as found by Europe PMC text mining. Sharing a sentence is not in itself a finding about the gene and the disease. The quoted sentences say what the papers report.
breast carcinoma (11 papers, 2010 to 2026). "In metastatic tumors, the exclusive presence of mutations in ATP8B1 and FRK in metastatic samples mirrors recent research on colorectal and breast cancers indicating that these genes play a role in tumor dissemination and metastatic colonization." (PMID 41590495, 2025). "For example, the growth of FRK over-expressing MCF-7 breast cancer cells was significantly inhibited, while the loss of FRK in normal mammary epithelial cells induced tumor formation." (PMID 29348886, 2017). "Our findings support the association of site-specific methylation of the FRK promoter with its reduced expression in breast cancer cells." (PMID 28077797, 2017). "Taken together, our data indicate that FRK is differentially expressed in breast cancer and the loss of FRK expression is more prevalent in the basal B breast cancers than other subtypes." (PMID 28077797, 2017). "Loss of FRK expression is more prevalent in the basal B breast cancers than other subtypes." (PMID 28077797, 2017). "However, we did not see any effect on STAT3 activation when the same mutation was introduced into FRK kinase domain and transfected in breast cancer cells." (PMID 29348886, 2017). "However, other mutations of FRK kinase domain increased FRK activity in breast cancer cells, as previously shown in hepatocellular adenomas." (PMID 29348886, 2017). "In order to evaluate whether the reactivation of FRK expression in breast cancer cells by epigenetic drugs was associated with promoter CpG demethylation, BT549 and Hs578T were evaluated after 5 days of 24 hourly treatments with DAC, and in the BT549, 24 hours post-treatment with Entinostat." (PMID 28077797, 2017). "Therefore, the restraint of EMT might be one of the mechanisms underlying the anti-migration/invasion effect of FRK in breast cancer cells." (PMID 29348886, 2017). "Mocetinostat and entinostat can induce re-expression of FRK at mRNA and protein levels in basal B breast cancer cells, contributing to tumor regression." (PMID 36969235, 2023). "It has been discovered that FRK mostly inhibits tumor cell growth in gliomas and breast cancer; by contrast, FRK contributes to the development of tumors in cases of pancreatic and hepatocellular carcinoma." (PMID 37745847, 2023). "Studies have shown that FRK can promote the invasion of liver cancer and pancreatic cancer cells, and inhibit the metastasis of breast cancer and glioma cells." (PMID 33435956, 2021). "As a member of the Src kinase family, FRK is involved in the progression of liver cancer, pancreatic cancer and breast cancer." (PMID 33435956, 2021). "Low levels of FRK show increased cell growth, colony formation and tumor growth, whereas high levels suppress tumor growth in breast cancer cell lines." (PMID 32710281, 2020). "Several studies have reported various potential mechanisms by which FRK acts as a tumor suppressor in glioma and breast cancer cells." (PMID 29348886, 2017). "We therefore examined if DAC would reactivate the expression of FRK in 4 breast cancer cell lines (BT549, HCC1395, Hs578T and MDA-kb2) with extensive FRK promoter methylation and low FRK expression." (PMID 28077797, 2017). "We also observed a decrease in menschenmyal markers such as fibronectin in Hs578T breast cancer cell line with the transient overexpression of FRK." (PMID 29348886, 2017). "Treatment of breast cancer cells with Entinostat and Mocetinostat resulted in 10 to 33-fold increase of FRK levels." (PMID 28077797, 2017). "Given the dramatic effect of constitutively active FRK-Y497F on cellular targets, we compared the effect of FRK-WT and FRK-Y497F on breast cancer cell proliferation." (PMID 29348886, 2017). "Mean transcript levels of SNAI2 were higher in the basal B breast cancer cells with low FRK transcript levels as compared to the Luminal cells (P<0.05)." (PMID 29348886, 2017).
breast carcinoma (continued). "We further performed in-silico analysis of breast cancer patient data from the Cancer Genome Atlas (TCGA) and established that the FRK proximal promoter region in tumors samples had a lower methylation density compared with the matched normal tissues." (PMID 28077797, 2017). "In this study, we investigated the expression of FRK and its promoter methylation status in breast cancer cell lines." (PMID 28077797, 2017). "Next, we transiently depleted FRK from FRK-positive breast cancer cell lines, SKBR3 and MCF-7 by RNAi." (PMID 29348886, 2017). "We recently reported the level of FRK transcript was low in the basal B breast cancers as compared to Basal A and Luminal cells." (PMID 29348886, 2017). "Our study also highlights the potential clinical significance of targeting FRK using epigenetic drugs specifically in basal B breast cancers which are usually triple negative and very aggressive." (PMID 28077797, 2017). "In the present study, we found that FRK expression was typically low in the basal B breast cancer cells that exhibit mesenchymal characteristics and provide evidence that FRK regulates EMT in breast cancer cells." (PMID 29348886, 2017). "With the exception of the HCC1419 cell line, the FRK promoter was highly methylated in breast cancer cell lines with low FRK expression." (PMID 28077797, 2017). "FRK was shown to interact with retinoblastoma protein (pRB), a tumor repressor gene, via the A/B pocket, inhibiting the proliferation of breast cancer cells." (PMID 28077797, 2017). "We examined the expression profile of FRK in a panel of 40 breast cancer cells representing all the major subtypes, as well as in 4 non-malignant mammary epithelial cell lines." (PMID 28077797, 2017). "Although FRK is thought to be a potential tumor suppressor in breast cancer, past studies investigating the tumor suppressive role of FRK were irrespective of breast cancer subtypes." (PMID 29348886, 2017). "While GATA-3 expressions were also low in all the FRK-low breast cancer cells, with exception of MDA-kb2 and the HCC1419, likewise this was not limited to the FRK-low cells." (PMID 28077797, 2017). "Little is known about the role and the mechanism of action of FRK in cell migration and invasion in breast cancer." (PMID 29348886, 2017). "Previous studies on the role of FRK expression in breast cancers were based on molecular subtypes of breast cancers." (PMID 29348886, 2017). "We performed RT-PCR to determine the expression levels of selected STAT3 target genes in FRK-overexpressing and the knockdown breast cancer cell lines." (PMID 29348886, 2017). "Previous reports demonstrated that FRK suppresses cell proliferation in breast cancer by various mechanisms, which include the stabilization of PTEN and BRCA1 and the internalization of EGFR." (PMID 29348886, 2017). "Because of the significant suppression of STAT3 activation by FRK (WT and Y497F), we checked if there was any correlation between FRK and pSTAT3 expression in a panel of 14 breast cancer cell lines." (PMID 29348886, 2017). "Pearson's correlation analysis run on 226 samples made up of 56 breast cancer cells showed that the FRK transcript levels negatively correlated with the transcript levels of VIM, CDH2, and TWIST1, with R-values of -0.28; -0.20; -0.25 respectively (P<0.001)." (PMID 29348886, 2017). "Based on our observation therefore promoter site-specific de-methylation of CpGs 11 and 12 is important for the up-regulation of FRK in breast cancer." (PMID 28077797, 2017). "It is likely that methylation CpG 12 interferes with binding of STAT5A to its DNA sequence on the FRK promoter hence repressing FRK expression in the breast cancer cells." (PMID 28077797, 2017). "It is possible to see an effect on cell proliferation if FRK-KM was stably knocked down in T47D breast cancer cells." (PMID 29348886, 2017).
breast carcinoma (continued). "It was previously reported that FRK acts as a tumor suppressor in breast cancer where it was shown to inhibit cell growth and suppresses tumorigenesis." (PMID 29348886, 2017). "The role of FRK in human cancer is unclear; however some reports have shown that its expression is lost in breast cancers and that its re-expression suppresses breast tumor growth." (PMID 28077797, 2017). "We found that FRK expression was significantly repressed in a proportion of basal B breast cancer cell lines." (PMID 28077797, 2017). "To understand the expression pattern of FRK in breast cancer, we examined the levels of the transcript and protein in a panel of 40 human breast cancer cell lines and 4 non-malignant mammary epithelial cell lines." (PMID 28077797, 2017). "We concluded that the repression of FRK in a subset of breast cancer cell lines was a consequence of methylation at specific CpG sites, -258 and -350." (PMID 28077797, 2017). "To determine the mechanism by which FRK regulates breast cancer cell migration and invasion, we employed kinome assays to identify potential FRK-regulated signaling pathways." (PMID 29348886, 2017). "The mean transcript expression of CDH1 and KRT18 were lower in the basal B breast cancer cells with low FRK transcript levels as compared to Basal A and Luminal cells that harbor high FRK transcript levels (P<0.05)." (PMID 29348886, 2017). "Stable overexpression of FRK in the Basal B/FRK-negative MDA-MB-231 breast cancer cell line resulted in reduced cell proliferation, migration, invasion, and colony formation." (PMID 29348886, 2017). "STAT5A transactivates the FRK promoter through its putative DNA binding motif, −355/−331.We concluded that in breast cancer cells STAT5A up-regulates the transcriptional expression of FRK." (PMID 28077797, 2017). "First, we found an inverse correlation between FRK and the mesenchymal marker, fibronectin in the Basal B breast cancer cell lines, MDA-MB-231, BT549 and Hs578T." (PMID 29348886, 2017). "Together, our results present the first evidence that site-specific promoter methylation contributes to the repression of FRK more so in basal B breast cancers." (PMID 28077797, 2017). "FRK was later shown to inhibit cell proliferation, invasion and colony formation in breast cancer cells devoid of pRB by the phosphorylation and stabilization of tumor suppressor PTEN." (PMID 28077797, 2017). "We investigated the expression pattern of FRK in breast cancer cell lines classified based on their morphology and invasiveness." (PMID 29348886, 2017). "We found that the mean transcript expression of VIM, CDH2, FN1, and TWIST1 were higher in the basal B breast cancer cells with low FRK transcript levels as compared to Basal A and Luminal cells that harbor high FRK transcript levels (P<0.05)." (PMID 29348886, 2017). "The FRK promoter region, +391 to -350, was extensively methylated in cells that expressed low as compared to high FRK levels, with exception of the luminal breast cancer cell lines, HCC1419 and ZR-75-1." (PMID 28077797, 2017). "We found that the expression of FRK was high in epithelial-like breast cancer cell lines and the normal mammary tissue, and is low or lost in in basal B breast cancer cell lines which display a mesenchymal phenotype." (PMID 29348886, 2017). "Thus, we examined the effect of FRK on the expression of well-known epithelial marker E-cadherin, and mesenchymal markers such as vimentin, fibronectin, slug and N-cadherin in breast cancer cells." (PMID 29348886, 2017). "To take a deeper look at the biological relevance of FRK in breast cancer, we analyzed the expression of FRK in a broader panel of 11 breast cancer cell lines classified into three subtypes (luminal, Basal B and Basal A) based on the cell morphology and invasive potential." (PMID 29348886, 2017). "We therefore hypothesized that DNA methylation decreased the expression of FRK in a subset of breast cancer cells." (PMID 28077797, 2017).
breast carcinoma (continued). "We have shown that FRK also suppresses cell migration and invasion of breast cancer cells." (PMID 29348886, 2017). "It is also unclear whether the expression of FRK correlates with any breast cancer clinical parameter." (PMID 29348886, 2017). "Taken together, our data demonstrate that FRK inversely correlates with mesenchymal markers in breast cancer cells and may, therefore, be a negative regulator of mesenchymal-like properties of breast cancer cells." (PMID 29348886, 2017). "Finally, we observed an inverse correlation between FRK expression and mesenchymal markers in a large cohort of breast cancer cells." (PMID 29348886, 2017). "Although, it is possible that we might see the effect if FRK was completely knockout from SKBR3 or MCF-7 breast cancer cell lines." (PMID 29348886, 2017). "We found about 75% inverse correlation between FRK and pSTAT3 in the 14 breast cancer cell lines tested, which aligns with our hypothesis that FRK is a negative regulator of STAT3 signaling." (PMID 29348886, 2017). "We opted to further characterize the effect of FRK on STAT3 signaling in breast cancer cells." (PMID 29348886, 2017). "FRK transcript levels were positively correlated with the transcript levels of E-cadherin and Cytokeratin 18 as well as in the breast cancer tissues mined from TCGA database where FRK correlated positively with E-cadherin in both normal and breast tumor tissue samples." (PMID 29348886, 2017). "Previous analyses of FRK in breast cancer cells/tissues reported differential expression patterns." (PMID 28077797, 2017). "However, our expression data corresponding to cell lines and TMA together indicate that the expression of FRK is enriched in epithelial cells/tissue and clearly downregulated in mesenchymal-like Basal B breast cancer cells." (PMID 29348886, 2017). "At present, the mechanisms regulating the expression of FRK in breast cancer are unknown." (PMID 28077797, 2017). "Based on these observations, we hypothesized that FRK might regulate EMT in breast cancer cells." (PMID 29348886, 2017). "However, in breast cancer cells, FRK suppresses cell proliferation by arresting cells in the G1 phase of the cell cycle; regulating PTEN protein stability and function; inhibiting EGFR signaling, and by regulating the stability and potentially the tumor suppressor function of BRCA1 protein." (PMID 29348886, 2017). "Therefore, the availability of a stratified mesenchymal-like subset of breast cancer patient samples in the TCGA database or any other database will be of help to further validate the correlation between FRK and the mesenchymal properties of breast tumor cells." (PMID 29348886, 2017). "Cell migration and invasion were reduced by FRK overexpression via inactivation of MAPK, AKT and JAK/STAT pathways and blockade of EMT in breast cancer cells, including inhibition of slug, vimentin, fibronectin, and upregulation of E-cadherin." (PMID 36969235, 2023). "FRK wild-type was reported to have growth inhibitory effects on MCF-7 and BT474 breast cancer cells." (PMID 29348886, 2017). "In breast cancer cells, ZR-75-1 and CAMA-1 the promoter region (+391/−959) was densely methylated even though the FRK (mRNA and protein) expression was high." (PMID 28077797, 2017). "Although FRK knockdown had little effect on STAT3 activation in SKBR3 and MCF-7 breast cancer cells, we noted that the knockdown of FRK led to the upregulation of Survivin mRNA levels in both cell lines." (PMID 29348886, 2017). "Among ER+ breast cancers, 15% harbored FGFR1 gene amplification and/or mRNA overexpression whereas 2.5, 1.9, 2.4, and 1.7% harbored amplification and/or mRNA overexpression of CRKL, HCK, FRK, and FGR, respectively." (PMID 30914635, 2019). "FRK has been shown to regulate cell proliferation of breast cancer and glioma cells, but its role in cell invasion in breast cancer has not been fully explored." (PMID 29348886, 2017).